IDO1 (indoleamine 2,3-dioxygenase 1)
Diseases named in the same sentence as IDO1 in open-access papers (continued):
Sharing a sentence is not in itself a finding about the gene and the disease.
melanoma (continued). "For instance, loss of the phosphatase and tensin homolog (PTEN), a common event in glioblastoma, prostate cancer, breast cancer, and melanoma, as well as indoleamine 2,3-dioxygenase 1 (IDO1) expression in the TME of soft tissue sarcomas, elicit resistance to ICB." (PMID 30497521, 2018). "While increased IDO1 expression has been associated with worse patient outcomes in a number of human malignancies including esophageal SCC, other tumors such as renal cell carcinoma, hepatocellular carcinoma, and melanoma demonstrate a correlation between IDO1 expression and improved survival." (PMID 29805749, 2018). "While kynurenine is produced by the tryptophan catabolizing enzyme TDO in several types of cancer including glioma, hepatocellular carcinoma and melanoma to promote immune evasion, we demonstrate here that IDO1 is equally capable of employing the AHR pathway in NSCLC and ovarian carcinoma cells." (PMID 24657910, 2014). "Initial evidence, in 2002, showed that IDO1 inhibitor 1MT could partly retard growth of mouse melanoma cells engrafted onto a syngeneic host." (PMID 24533148, 2014). "Specifically, IDO1 inhibition by epacadostat leads to an adverse protection of melanoma cells against IFN-γ-activated T cells, caused by Trp replenishment in the TME that prevents the downregulation of the transcription factor MITF responsible for melanoma cell survival." (PMID 41262240, 2025). "Standard chemotherapeutic drugs may promote immune evasion by activating the KP; in HNSCC cells, cetuximab induces IDO1, and in melanoma, the anti‐PD1 monoclonal antibody (mAb) nivolumab can induce IL4I1 and IDO1, with nivolumab treatment linked to AhR activation." (PMID 40103267, 2025). "Additionally, melanoma-induced IDO1 expression and CD83 downregulation could represent a new tumor escape mechanism." (PMID 38791968, 2024). "However, studies on IDO1 expression in primary human melanoma are incomplete and conflicting." (PMID 38794128, 2024). "In preclinical models, a dual inhibitor of topoisomerase II and IDO1 —a drug conjugate of D-1MT, an IDO inhibitor and paclitaxel, and a drug conjugate of D-1MT and gallic acid (GA-1MT) —were described to have potent antiproliferative activity against melanoma cells." (PMID 37345056, 2023). "Furthermore, through the use of selective inhibitors targeting IDO1 and COX-2, we successfully demonstrated that the melanoma cell line’s ability to impair iNKT cell activation and functions was attributed to the up-regulation of IDO1 expression and PGE2 production." (PMID 37444608, 2023). "In addition, primary and metastatic melanoma cells can express IDO1." (PMID 35408802, 2022). "Besides IDO1 induction in peri-tumoral DCs, melanoma cells themselves can express IDO1." (PMID 35408802, 2022). "Furthermore, IDO1 expression in primary cutaneous melanoma correlates with Breslow thickness, and IDO1 expression in antigen-presenting cells correlates negatively with progression-free survival of patients with melanoma." (PMID 35408802, 2022). "In addition, IDO1/TDO activation causes kynurenine (Kyn) accumulation in the TME, which activates the aryl hydrocarbon receptor (AhR), orienting T-cell differentiation into FoxP3+ regulatory T cells and the resultant melanoma immune escape." (PMID 36003368, 2022). "Importantly, a negative prognostic role of IDO1+ cells in SLN of patients with melanoma has been reported according to previous hypotheses that IDO1 expression represents a melanoma immune escape mechanism." (PMID 35408802, 2022). "In addition to mitochondria-regulating agent metformin, drugs targeting amino acid metabolism, in particular, the inhibitors of indoleamine 2,3-dioxygenase 1 (IDO1) enzyme, have been applied in multiple clinical trials in combination with anti-PD-1 immunotherapy in melanoma." (PMID 36003368, 2022).
melanoma (continued). "Similarly, melanoma patients who were resistant to previous treatment with radiotherapy plus ipilimumab showed increased plasma Kyn/Trp ratio, further confirming that Ido-1 may be activated as escape mechanism to immunotherapy induced anti-tumor response." (PMID 36419183, 2022). "Thus, in response to inflammatory signals under pathophysiological conditions IDO1 is highly up regulated by the immune system, and over-expression of IDO1 improves detection in different types of cancers, including melanoma, pancreatic, ovarian, and colorectal." (PMID 36551617, 2022). "However, the negative results of the phase III clinical trial of the would-be first-in-class IDO1 inhibitor (epacadostat) in combination with an anti-PD1 antibody (pembrolizumab) in patients with advanced malignant melanoma call for a better understanding of the role of IDO1 inhibition." (PMID 33557876, 2021). "The aims of this article are, (i) to introduce the current status of clinical testing of IDO1 inhibitors (ii) to review representative data of epacadostat and (iii) to discuss some open questions raised from the failure of epacadostat in advanced malignant melanoma." (PMID 33557876, 2021). "Additionally, soluble melanoma-derived Wnt5a can alter local DC metabolism, leading to increased indoleamine 2,3-dioxygenase 1 (IDO) enzymatic activity and suppressed IL-6 and IL-12 production, thereby creating an immunosuppressive environment that promotes Treg development." (PMID 32290124, 2020). "Moreover, it seems that IDO-1 positive melanoma patients have a poor outcome." (PMID 32296574, 2020). "In addition, IDO1 revealed a pro-proliferative effect on melanoma cells." (PMID 31315643, 2019). "Combining CAI with IDO1/AhR inhibitors could lead to a more selective anti-tumor immunoreaction, which was confirmed in a specialized coculture system consisting of B16 melanoma cells expressing ovalbumin (OVA) antigen (B16-OVA) and OVA-specific CTLs derived from OT-1 transgenic mice." (PMID 31511064, 2019). "In particular, combining IDO1 inhibitors with PD-1 or CTLA-4 blockade has demonstrated enhanced anti-tumor effects in early phase clinical trials, particularly in melanoma and advanced GBM models." (PMID 41233805, 2025). "Bufalin disrupts the ATP1A1-Cav-1 complex, reversing drug resistance in melanoma, while cardiac glycosides inhibit STAT1-mediated IDO1 expression, demonstrating synergy with immune checkpoint inhibitors." (PMID 40821775, 2025). "In human melanoma cells, inhibition of GLI1 expression prevented the induction of IDO1 expression in response to IL6/STAT3 and IFNγ/STAT1 signaling." (PMID 39962447, 2025). "To test and validate our findings in skin cancer models with a documented and pathophysiologically relevant role for IDO1 and oncogenic GLI expression, we shifted our focus to human melanoma cells with JAK/STAT signaling-dependent expression of IDO1." (PMID 39962447, 2025). "To that end, we generated conditioned media of melanoma cells treated with solvent control, inhibitors of IDO1 or GLI alone or in combination with IFNγ (to induce IDO1 expression and kynurenine production)." (PMID 39962447, 2025). "This is examined in connection with IDO-1 and IL-6 expression in response to IFN-γ or UVB stimulation, both crucial factors of the melanoma tumor microenvironment (TME)." (PMID 39062529, 2024). "A study examining the expression of IDO1, PD-L1, and FOXP3-positive regulatory T cells in the melanoma tumor cells showed that these upregulations were driven by CD8+ T cells." (PMID 38632994, 2024). "The mutual influence between human melanoma cells and endothelial cells was investigated by means of co-cultures by assessing TDO2 and IDO1 expression in A375 and HUVECs." (PMID 38794128, 2024). "Then, CD83+ LCs, IDO1+/− (real mature SLN LCs and regulatory/inhibitory SLN LCs) migrate to SLN, possibly modulating the escape mechanism in melanoma." (PMID 38791968, 2024).
melanoma (continued). "The current investigation not only establishes the correlation between IDO-1 upregulation and the topical Trp/Kyn ratio but also underscores the pivotal role of IFN-γ in the transformation and progression of melanoma." (PMID 39062529, 2024). "Lastly, datasets from patient melanomas with acquired ICB resistance and IDO1 inhibition are scarce, hindering such clinical corroboration." (PMID 36812891, 2023). "We reported that the inhibitory effect exerted by melanoma cells was mainly due to COX-2 activity and IDO1 expression, resulting in the release of IFN-γ from activated iNKT cells." (PMID 37444608, 2023). "These functional data strongly suggest that IDO1 and COX-2 play important roles in the immunosuppressive activity of melanoma cells against iNKT cell activity." (PMID 37444608, 2023). "Epacadostat (IDO1 selective inhibitor) and pembrolizumab showed promising antitumor activity in the early phase ECHO-202/KEYNOTE-037 study in advanced melanoma." (PMID 36798123, 2023). "In a phase-I/II trial, a more potent IDO1 inhibitor, BMS-986205, was added to nivolumab or nivolumab plus ipilimumab treating 627 patients with advanced cancers including melanoma, and results are awaited (NCT02658890)." (PMID 37345056, 2023). "Recent findings suggest that WNT5a released from melanoma cells prompts paracrine WNT5-β-catenin signalling in DCs, resulting in an upsurge of the immunoregulatory enzyme indoleamine 2,3-dioxygenase-1 (IDO), which is pivotal in tumour-induced immune tolerance." (PMID 38136392, 2023). "Because IDO1 activity leads to degradation of TRP in the TME, we measured the level of TRP in the culture medium after T cell treatment of melanoma cultures at a 1:10 T cell:tumor ratio, where we observed the biggest range of tumor sensitivities." (PMID 36812891, 2023). "We first investigated by fluorescent immunocytochemistry IDO1 expression in SLN LCs, the first DC subset to encounter cutaneous primary melanomas." (PMID 35408802, 2022). "In syngeneic mice model of melanoma, depletion of Kyn in both plasma and tumor by Kyn-degrading enzymes kynureninase reduced Kyn levels in IDO1, TDO2 and IDO1/TDO2-expressing cancer cells and augmented effector T cells in tumor, without impact on Trp levels." (PMID 35173722, 2022). "The data indicate increased Trp metabolism by TDO, IDO1, and IDO2 enzymes both in the direction of NAD+ synthesis and in the direction of KYNA branching in melanoma patients." (PMID 36012419, 2022). "A six-gene IFN-γ signature (including IDO1, CXCL10, CXCL9, HLA-DRA, STAT1, and IFNG) was identified in a melanoma cohort of the KEYNOTE-001 study to predict response to pembrolizumab." (PMID 35222540, 2022). "Indoleamine 2,3-dioxygenase 1 (IDO1) is overexpressed in numerous tumors, including melanoma, breast cancer, and CRC." (PMID 35571116, 2022). "In melanoma TME, IDO1 and TDO pathways are hyper-activated in both melanoma cells and tumor-infiltrating lymphocytes by immune cell-derived IFN-γ, which reduces tryptophan in TME." (PMID 36003368, 2022). "Analysis of IDO1/TDO2 expression in the Cancer Genome Atlas (TCGA) database revealed that both IDO1 and TDO2 were upregulated in TNBC and melanoma relative to normal breast and skin tissues." (PMID 35780226, 2022). "In this study the impact of the serum Kyn/Trp ratio and IDO1 expression by immune cells of the lymph node and peripheral blood compartment on clinical outcome was investigated in a cohort of stage I-III melanoma patients with long-term follow-up." (PMID 34557196, 2021). "By LASSO Cox regression analysis, we constructed a prognosis model based on 5-mRNA (SRGN, IDO1, RARRES3, CCL4, HLA-DPB1), which has great predictive value for the overall survival of melanoma." (PMID 34805163, 2021). "As for anti-PD-1 blockade, the IFN-γ gene signature (IDO1, CXCL10, CXCL9, HLA-DRA, STAT1, and IFNG) predicts the response to anti-PD-1 therapy in multiple tumors, including melanoma." (PMID 34439264, 2021).
melanoma (continued). "This might suggest that even the high mutation burden subset of melanoma, which shows over-expression of both IDO-1 and IDO-2 but not TDO-2, does not respond to IDO-1 inhibitors and over-expression of all three genes are necessary for response to IDO-1 inhibitors." (PMID 34367262, 2021). "When studying IL4I1 levels in ICB-treated advanced melanoma patients, it was noted that nivolumab therapy correlated with the induction of both IL4I1 and IDO1 and resulted in AhR activation." (PMID 34944851, 2021). "Indoximod is a competitive IDO1 inhibitor and has been granted orphan-drug designation by the US FDA for the treatment of stage IIb to stage IV melanoma." (PMID 33883013, 2021). "In mouse splenic pDCs Wnt5a was found to upregulate the surface expression of indoleamine 2,3-dioxygenase-1 (IDO), which plays a significant role in DC tolerogenesis in melanoma." (PMID 33919546, 2021). "The same treatment regimen of IDO1/AhR inhibitor with IFNγ reduced tumor growth and prolonged the overall survival of NOD/SCID mice bearing B16 melanoma tumors." (PMID 33379189, 2020). "As a result of silencing IDO1, PDL-1 an activation of immune response was determined in several cancer models (breast, bladder, colon, orthotopic and metastatic liver cancer, melanoma) showing good antitumor response." (PMID 32012775, 2020). "A preclinical study demonstrated that up-regulation of tumor IDO1 expression was driven by CD8+TILs in Melanoma and the infiltration of CD8+TILs was positive correlated with the expression of tumor IDO1 expression." (PMID 32733806, 2020). "In the KEYNOTE-001 study, six gene signatures of INFG-related genes (IDO1, HLA-DRA, STAT1, CXCL9, IFNG and CXCL10) were previously developed in melanoma patients." (PMID 32107458, 2020). "This line of investigation led to the discovery that the melanoma-derived WNT5A ligand both promotes the expression and supports the enzymatic activity of IDO1 in local DCs by inducing the synthesis of its required heme prosthetic group, protoporphyrin IX." (PMID 31921140, 2019). "Indoximod (1-methyl-D-tryptophan, 1MT, NLG-8189) is the most-studied IDO1 inhibitor and has been granted orphan-drug designation by the US FDA for the indication of stage IIb to stage IV melanoma." (PMID 30068361, 2018). "IDO1 expression was evaluated in human BCC and melanoma models by qPCR and Western blot analyses." (PMID 39962447, 2025). "Taken together, these data provide evidence that HH/GLI cooperates with JAK/STAT signaling to synergistically activate the expression of the immunosuppressive enzyme IDO1 in melanoma and non-melanoma skin cancer patients." (PMID 39962447, 2025). "Our in silico RNA-seq data analyses of human normal and malignant skin corroborate the presence of the identified molecular mechanism of a HH/GLI-dependent IDO1 induction in melanoma and non-melanoma skin cancer patients." (PMID 39962447, 2025). "Finally, we supplemented our proteome and secretome profiling with measurements of IDO1, LGMN, and cathepsin activity in DC2s and DC3s, including tumor tissue samples from melanoma patients." (PMID 40789452, 2025). "Indeed, iNKT cells expanded from PBMCs and co-cultured with melanoma tumor cells exhibited a dampened NKG2D expression and reduced cytotoxic capacities in an IDO-1- and PGE2-dependent manner." (PMID 41562072, 2025). "We identified IDO1 as a target gene of cooperative GLI-STAT activity in BCC and melanoma." (PMID 39962447, 2025). "For instance, ECHO-301/KEYNOTE-252 phase 3 trial showed that combining IDO1 inhibitor (Epacadostat) with pembrolizumab did not enhance progression-free survival or overall survival compared to pembrolizumab alone in melanoma patients." (PMID 41233805, 2025). "In summary, we characterized tumor-induced changes in the DC2 proteome of which several are associated with immunosuppression and protumor effects, including IDO1 and LGMN, through which melanoma-induced DC3s could impair antitumor immunity." (PMID 40789452, 2025).
melanoma (continued). "• IDO1 inhibition: The phase III ECHO-301/KEYNOTE-252 trial of epacadostat plus pembrolizumab in melanoma was negative, and no IDO1-targeting regimen has produced a positive efficacy signal in glioblastoma." (PMID 41583467, 2025). "At flow cytometry analyses, IDO1 expression was documented in both melanoma-positive and melanoma-negative SLN LCs." (PMID 38791968, 2024). "Conversely, the inhibition of IDO1 in both melanoma cells had no discernible impact on HUVEC growth." (PMID 38794128, 2024). "Recently, IDO1 inhibitors have been included in clinical trials in combination with chemotherapy and immunotherapy, such as anti-CTLA-4 and/or PD-1, to restore anti-melanoma immunity." (PMID 38791968, 2024). "This hypothesis might be consistent with the frequencies detected for the four SLN LCs subsets in melanoma patients, being CD83+IDO1- and CD83-IDO1- the main SLN LCs subsets, and CD83+IDO1+ SLN LCs, the lower one, slightly affected by melanoma." (PMID 38791968, 2024). "An IDO1 enzyme inhibitor was also shown to improve the efficacy of anti-CTLA-4 and anti-PD-L1 antibody therapy in a mouse B16 melanoma model and further induce the proliferation, survival, and functions of antitumor immune cells in vitro and enhance antitumor immunity in vivo against Pan02 cells." (PMID 38791327, 2024). "In a phase I study of atezolizumab for patients with advanced melanoma, elevated expression of IFN-γ as well as IFN-γ-inducible genes (for example, indoleamine 2,3 dioxygenase 1 [IDO1] and C-x-C motif chemokine ligand 9 [CXCL9]) in pre-treatment tumours were demonstrated in responding patients." (PMID 39530091, 2024). "We further investigated whether IDO1 and COX-2 activity is responsible for the inhibition of iNKT cell proliferation mediated by melanoma cells." (PMID 37444608, 2023). "Still, the phase III clinical trial of IDO1 inhibitor plus anti‐PD‐1 mAb in advanced melanoma failed to improve overall survival, compared with anti‐PD‐1 monotherapy, which implied the requirement for further improving IDO1 inhibition strategies." (PMID 37403792, 2023). "The IDO1 inhibitor epacadostat showed promising results in early clinical trials but failed to prove efficacy in a phase 3 trial in advanced melanoma (ECHO-301/Keynote-252 study)." (PMID 36980787, 2023). "In an immunocompetent B16-OVA melanoma model, while we did not observe tumor acceleration upon IDO1 inhibition (likely because of simultaneous tumor cell and immune cell protection), there was again no improved tumor control, in line with a previous study." (PMID 36812891, 2023). "αGC-treated PBMC were co-cultured with melanoma cell lines in the presence or absence of increasing concentrations of IDO1 and COX-2 inhibitors (1MT and rofecoxib, respectively)." (PMID 37444608, 2023). "The expression of IDO1 in single GCs was not reported by a previous study that stained benign lymphadenopathies and tumor-draining lymph nodes from patients with melanoma and breast carcinoma." (PMID 36830609, 2023). "The first Phase III clinical trial of an IDO1 inhibitor administered with anti-PD-1 to melanoma patients failed to improve their survival." (PMID 36188218, 2022). "In a cohort of melanoma patients receiving adjuvant treatment with IFN- α2b, levels Kyn/Trp levels, that is a biomarker of Ido-1 activation, were monitored under treatment and they resulted positively increased in plasma from treated patients as compared to untreated cohort." (PMID 36419183, 2022). "The ECHO-301/KEYNOTE-252 trial found that treatment with the IDO1 inhibitor Epacadostat did not improve overall survival or progression free survival in melanoma, which brings into question the utility of IDO inhibitors in a clinical setting." (PMID 36479131, 2022). "Indeed, the combination of IDO1 inhibitor with CTLA-4 and PD-1/L1 antibodies demonstrated synergistic antitumor activity in glioma and melanoma mice models." (PMID 35173722, 2022).